ADAM17 (ADAM metallopeptidase domain 17)
Diseases named in the same sentence as ADAM17 in open-access papers (continued):
Sharing a sentence is not in itself a finding about the gene and the disease.
Hypertension (21 papers, 2014 to 2025). The presence of chronic increased pressure in the systemic arterial system. "ADAM17 orchestrates many different signaling pathways linked to hypertension and other CVDs as showed in this review." (PMID 36310604, 2022). "ADAM17 also cleaves most of the ligands of the epidermal growth factor receptor (EGFR) which have been associated with hypertension, atherogenesis, vascular dysfunction, and cardiac remodeling." (PMID 33330676, 2020). "Inhibition of ADAM17 attenuated inflammation and its associated hypertension, but it may impact the release of L-selectin and other cell adhesion molecules which may affect normal cellular mechanisms of growth, contact inhibition, and apoptosis." (PMID 32848763, 2020). "In hypertension, ADAM17 induces the release of TNF-α and the shedding of ACE2, making it a key point in the treatment of hypertension." (PMID 41050403, 2025). "More studies are required to better understand the role of miR-145/ADAM17 in the pathophysiology of vascular remodeling in vivo and in the development of treatments for vascular remodeling due to hypertension." (PMID 37521117, 2023). "ADAM17, as the most important sheddase, is also involved in the vascular remodeling in the case of hypertension." (PMID 37521117, 2023). "It has been shown that ADAM17 knockdown in the brain can restore ACE2 activity and attenuate the development of hypertension, suggesting that ADAM17-induced ACE2 cleavage is involved in the development of neurogenic hypertension." (PMID 36310604, 2022). "Chronic knockdown of ADAM17 in the brain was able to blunt the development of hypertension and restored ACE2 activity and baroreflex function." (PMID 34163462, 2021). "Together these data support the ADAM17-mediated shedding of inflammatory cytokines contribution to the development of hypertension." (PMID 32848763, 2020). "Increased ADAM17 activity was detected in several pathologies, such as diabetes mellitus, hypertension, inflammatory processes, cardiovascular disorders, neurological and oncological diseases." (PMID 33126657, 2020). "In this review, we discuss the role of ADAM17 in inflammation-mediated hypertension in the brain and periphery." (PMID 32848763, 2020). "This narrative review provides an overview of the role of ADAM17, with a special focus on its cellular regulation on neuronal and peripheral inflammation-mediated hypertension." (PMID 32848763, 2020). "Chronic activation of the renin angiotensin system (RAS) and increased binding of Angiontesin-II (Ang-II) to the Ang-II type 1 receptor (AT1R) is a crucial mechanism leading to ADAM17 activation, promoting inflammation and hypertension." (PMID 32848763, 2020). "A knockdown of ADAM17 in the DOCA-salt hypertensive model prevented the decline in ACE2 in the brain and attenuated hypertension, whereas an overexpression of ACE2 was associated with reduced ADAM17 levels." (PMID 33126657, 2020). "The rise in ADAM17 levels has both central and peripheral implications in inflammation-mediated hypertension." (PMID 32848763, 2020). "The potential role of ADAM17-mediated shedding of IL-6R and its role in IL-6 trans-signaling-mediated inflammation and its impact on hypertension needs investigation." (PMID 32848763, 2020). "Researchers also found that upregulation of TPRC3 enhances EGFR transactivation, which is involved in hypertension-induced cerebrovascular remodeling by the signaling pathway TRPC3/ADAM17." (PMID 31871548, 2019). "Moreover, the ADAM17 protein expression of the Pb + hypertension group firstly increased in the PFC at 4 w exposure, following in the hippocampus and hypothalamus at 8 w exposure." (PMID 39853035, 2025). "The shedding of ACE-2 induced by ADAM17 diminishes the protective effect of ACE-2 in hypertension." (PMID 38339115, 2024). "However, the role of miR-145/ADAM17 feedback loop in the vascular remodeling in case of hypertension is poorly understood." (PMID 37521117, 2023).
Hypertension (continued). "However, the role of miR-145/ADAM17 pathway in the vascular remodeling in case of hypertension and the potential mechanisms is still poorly understood." (PMID 37521117, 2023). "So, knockdown of ADAM17 in the brain can blunt the development of hypertension." (PMID 36310604, 2022). "In an interesting study using a mouse model of Ang-II-induced hypertension without smooth muscle ADAM17 participation, caused by gen deletion or systemic pharmacological inhibition of ADAM17, the vascular hypertrophy and perivascular fibrosis were reduced." (PMID 36310604, 2022). "The increase of ADAM17 showed an essential role in the signal transduction for cardiovascular remodeling associated with ER stress however not for hypertension in Ang-II-treated mice." (PMID 36310604, 2022). "Studies also have showed limitations to reveal the ADAM17 as a therapeutic target in hypertension." (PMID 36310604, 2022). "The caveat with chronic knockdown of ADAM17 is that there are numerous substrates for ADAM17 and hence, ADAM17 affects many systems, including cytokines that may play a role in hypertension." (PMID 34163462, 2021). "Finally, it highlights the importance of ADAM17 with regards to the biology of inflammatory cytokines and their roles in hypertension." (PMID 32848763, 2020). "In addition, we showed that blocking B1R or ADAM17 activation within the brain is beneficial in attenuating hypertension." (PMID 33375653, 2020). "Activation of central bradykinin B1 receptors also leads to ADAM17 activation resulting in immune cell infiltration, microglia activation, and cytokine production within the central nervous system (CNS), and ultimately neuroinflammation-mediated hypertension." (PMID 32848763, 2020). "Inflammation and ADAM17 play both a central and peripheral role to elicit hypertension." (PMID 32848763, 2020). "Finally, ADAM17 knockdown inhibited hypertension-induced cardiac hypertrophy and fibrosis." (PMID 33117379, 2020). "Importantly, inhibition of ADAM17-mediated inflammation could be a potential target for the treatment of drug-resistant hypertension." (PMID 32848763, 2020). "Collectively, the results exhibited that ADAM17 is a major proteolytic enzyme of TREM2 regarding Pb and AngII (hypertension) treatment." (PMID 39853035, 2025). "For instance, upregulated ADAM17 activity reduced TREM2 expression and exacerbated neuroinflammation in a lead exposure‐induced hypertension mouse model." (PMID 41476737, 2025). "ADAM10 or ADAM17, the enzymes cleaving TREM2, were detected to elucidate the mechanism of TREM2 decrease in mice with hypertension, Pb alone, or co-exposure." (PMID 39853035, 2025). "ACE2, ADAM17, and CTSL all showed a clear trend of joint upregulation in healthy tissues compared with DCM, ICM, and hypertension." (PMID 37259108, 2023). "There are limited studies investigating the relationship of Cluster of differentiation 56 (CD56), A disintegrin and metalloprotease 17 (ADAM17) and Fibroblast growth factor 21 (FGF21) with hypertension and PE." (PMID 37374349, 2023). "In this review, we focused on the central and peripheral effects of ADAM17-mediated shedding of inflammatory cytokines such as IL-6, TNF-α, and FKN, and their possible role in hypertension." (PMID 32848763, 2020). "Next, to further elucidate whether ADAM10 or ADAM17 were mainly involved in the proteolytic shedding of TREM2 following hypertension and Pb exposure, we examined the protein expressions of ADAM10 and ADAM17 in vivo." (PMID 39853035, 2025). "ADAM17 has gained increasing attention for its involvement in various cardiovascular conditions, including atherosclerosis (AS), acute myocardial infarction (AMI), cardiomyopathy, aortic aneurysm, and hypertension." (PMID 41050403, 2025). "All findings indicated ADAM17 might be a main proteolytic enzyme regarding the TREM2 decrease induced by Pb and AngII (hypertension) exposure." (PMID 39853035, 2025).
Hypertension (continued). "Our findings provided new insights into the complex interplay between hypertension, Pb exposure, and neuroinflammation as well as highlight the potential role of TREM2, ADAM17, and miR-26a-5p as therapeutic targets for neuroinflammation in hypertensive populations with Pb exposure." (PMID 39853035, 2025). "In addition, inhibition of other ADAM17 activators for instance ROS, as showed by our group using lipoic acid or a SOD mimetic, tempol, were able to prevent the hypertension development in a DOCA-salt hypertension model." (PMID 36310604, 2022). "This occurs via a signaling mechanism involving ADAM17-mediated shedding which is independent of hypertension." (PMID 27803674, 2016). "In addition, using Neuro2A cells (neuroblastoma cell line) and a DOCA-salt model of hypertension, the antioxidant therapy preserved ACE2 compensatory role by breaking the feedforward cycle between oxidative stress and ADAM17 especially due to the oxidative stress decreasing." (PMID 36310604, 2022). "Increase in ADAM17 levels in the paraventricular nucleus (PVN) and subfornical organ (SFO) have been reported to elevate the expression of inflammatory (TNF-α, IL-β, and COX-2) and excitatory mediators, which drive the sympathetic excitation-mediated hypertension and heart failure." (PMID 32848763, 2020).
Alzheimer disease (20 papers, 2011 to 2025). A progressive, neurodegenerative disease characterized by loss of function and death of nerve cells in several areas of the brain leading to loss of cognitive function such as memory and language. "Reflecting this important role in signaling, dysregulated ADAM17 activity is linked to many human diseases, including immunodeficiency, inflammatory bowel disease, rheumatic arthritis, cancer, and Alzheimer's disease." (PMID 40885391, 2025). "In the context of neurodegenerative diseases, ADAM17 is mainly implicated in the pathology of Alzheimer’s disease (AD), a progressive disorder characterized by cognitive dysfunction and amyloid β (Aβ) accumulation." (PMID 41050403, 2025). "Recent studies have highlighted the significant role of ADAM17/TACE (encoded by ADAM17/TACE) in the pathogenesis of Alzheimer's disease (AD)." (PMID 40327644, 2025). "Both ADAM10 and ADAM17 have been implicated in the development of neurodegenerative diseases such as Alzheimer’s disease." (PMID 27549131, 2016). "Moreover, recent reports have described the role of genetic polymorphisms in ADAM17/TACE in the sporadic form of Alzheimer’s disease, as well as their impact on the clinical phenotype of patients." (PMID 41465142, 2025). "Moreover, endothelial senescence and Alzheimer's disease (AD) were associated with ANG II-activated ADAM17, connecting both proteins to microvascular aging and disrupted biological barriers." (PMID 34248502, 2021). "This study demonstrates that the Alzheimer’s disease risk factor iRhom2/RHBDF2 is a modifier of microglial TREM2 proteolysis and establishes ADAM17 as a physiological TREM2 protease in microglia." (PMID 40081988, 2025). "The results from the present study indicate that cerebrovascular ADAM17 plays a role in the pathogenesis of Alzheimer’s disease (AD)." (PMID 36937050, 2023). "Using qPCR, we confirmed glutamate-induced upregulation, normalized by candesartan, of a number of these genes, including several factors with fundamental roles in APP metabolism and Alzheimer’s disease, such as ADAM metallopeptidase domain 17 and APOE." (PMID 26822027, 2016). "Here, we hypothesized that cerebrovascular ADAM17 plays a role in the pathogenesis of Alzheimer’s disease (AD)." (PMID 36937050, 2023). "In particular, we propose that loss of function mutations upstream of NF-κB such as ADAM17, SHARPIN, HOIL, or OTULIN affect NF-κB-activity in Alzheimer’s disease (AD) patients, in turn driving anatomical defects such as shrinkage of entorhinal cortex and the limbic system in early AD." (PMID 35983068, 2022). "On the other hand, a study in the APP/PS1 mouse model of Alzheimer's disease demonstrated that overexpression of ADAM17 could influence cerebrovascular functions and cognitive abilities, highlighting its potential role in AD pathology and as a therapeutic target." (PMID 38963109, 2024). "Elevated levels of ADAM17 were observed in the cerebrospinal fluid of patients with neoplastic meningitis, mild cognitive impairments (MCI), and Alzheimer’s disease (AD))." (PMID 36293469, 2022). "ADAM17, BACE1, CAPN1, CDK5, EIF2AK3, GRIN2B, and GSK3B were enriched in the Alzheimer disease pathway (hsa05010)." (PMID 33807157, 2021). "However, using an extended and even more recent list of GWAS results from the European Alzheimer’s disease DNA biobank (EADB) project published as preprint reveals several new connections, i.e. for ADAM17 & USP6NL (both miR-129-5p), CTSB & EED (miR-138-5p), and ANK3 & PLEKHA1 (miR-195-5p)." (PMID 36038535, 2022).
glioblastoma (20 papers, 2011 to 2025). The most malignant astrocytic tumor (WHO grade IV). "In this context, miR-145 was described as a direct target of ADAM17 in glioblastoma cells, and reciprocal regulation of ADAM17 and miR-145 is believed to drive the invasiveness of this tumor entity." (PMID 36293469, 2022). "LPS-stimulated IFN-DCs from glioblastoma patients were characterized by nearly a threefold greater activity of TACE/ADAM-17, than donor-derived IFN-DCs." (PMID 32326230, 2020). "The invasion ability of glioblastoma multiforme (GBM) cells was drastically inhibited when the ADAM17 was knocked down." (PMID 32610677, 2020). "In this study, we analyzed mTNFα expression regulation both at the transcriptional and post-translational levels to demonstrate for the first-time high expression and activity of TACE/ADAM-17 in IFN-DCs from glioblastoma patients." (PMID 32326230, 2020). "We have focused on the role of two closely related metalloproteinases ADAM10 and ADAM17 due to their high expression in glioblastoma and GSCs and their ability to activate cytokines and growth factors." (PMID 27541285, 2017). "High levels of ADAM17 have been reported in a variety of cell lines and clinical tissue samples, including breast, colon, prostate and glioblastoma." (PMID 23076445, 2013). "It is conceivable that in the necroses of glioblastoma, ADAM17-mediated shedding of membrane CD163 from macrophages occurs which could explain the presence of the large amounts of extracellular CD163 we observed in necrotic tissue areas in this study." (PMID 40191733, 2025). "ADAM-10 and ADAM-17 are overexpressed in the glioblastoma microenvironment." (PMID 36980765, 2023). "Glioblastoma patient IFN-DCs showed lower cytotoxicity against autologous glioblastoma cells sensitive to TNFα/TNFR1-mediated lysis, which was associated with low TNFα mRNA expression and high TACE/ADAM-17 enzyme activity." (PMID 32326230, 2020). "Additionally, ADAM17 has been shown to function as an oncogene, promoting U87 glioblastoma stem cell migration and invasion." (PMID 25364437, 2014). "Moreover, ADAM17 KD decreases AKT signaling in glioblastoma cells." (PMID 36293469, 2022). "This study suggests that sLRIG3, modulated by ADAM17 in GBM tumor cells, interacts with the CUB1 domain of NETO2 and plays a key role in attenuating the tilt towards an M2-dominant TAM population, thus remodelling the heterogeneous glioblastoma microenvironment, and suppressing GBM malignant growth." (PMID 36639372, 2023). "Based on the data obtained, we performed comparative analysis of TACE/ADAM-17 expression on IFN-DCs from healthy donors and glioblastoma patients 2 h after LPS treatment." (PMID 32326230, 2020). "GSCs have not only increased expression of ADAMs compared to NSCs but also elevated receptor tyrosine kinases whose ligands are shed by ADAM10 and ADAM17, in particular EGFR, which is often upregulated in glioblastoma." (PMID 27541285, 2017). "We, along with others, have previously identified overexpression of the metalloproteinases ADAM10 and ADAM17 in glioblastoma, where increased ADAM10 or ADAM17 expression correlates with poorer prognosis." (PMID 27541285, 2017). "Previous reports using commercial glioblastoma cell lines suggest that ADAM10 and ADAM17 inhibition decrease tumour growth and invasiveness but these do not specifically address the behaviour of the tumourigenic cells." (PMID 27541285, 2017). "As ADAM10 and ADAM17 are overexpressed in glioblastoma where they can act to increase the EGF concentration in the niche then anti-ADAM10 and ADAM17 treatment may mediate migration out of the niche by reducing local EGF concentrations." (PMID 27541285, 2017). "verified reciprocal control of ADAM17/EGFR/Akt signaling and miR-145 drives glioblastoma multiforme (GBM) invasiveness." (PMID 36033536, 2022).
glioblastoma (continued). "PMA also increased degradation of the mature processed form of ADAM17/TACE, but not ADAM10, in HEK293 cells, and promoted the translocation of ADAM10 to the cell membrane in glioblastoma cells." (PMID 21586144, 2011). "A negative correlation has been found in glioblastoma between the genetic signature of the epithelial-to-mesenchymal transition (EMT) and that of CD133, suggesting that ADAM10 and ADAM17 inhibition might activate the transition, differentiating the cells and increasing cell migration and invasion." (PMID 27541285, 2017).